FPR2 (formyl peptide receptor 2)
Diseases named in the same sentence as FPR2 in open-access papers (continued):
Sharing a sentence is not in itself a finding about the gene and the disease.
heart failure (7 papers, 2020 to 2024). Inability of the heart to pump blood at an adequate rate to meet tissue metabolic requirements. "Over the past decade, several compounds targeting FPR2 have been developed to treat the proinflammation that accompanies heart failure by driving resolution processes." (PMID 39706266, 2024). "FPR2 is an attractive target for the pharmaceutical industry because of agonist-specific activation of proresolution mechanisms with a compound currently in clinical trials for heart failure." (PMID 39706266, 2024). "Indeed, a Phase I trial has been concluded for the compound BMS-986235, a selective FPR2 agonist with tissue-protective properties in experimental heart failure." (PMID 33804219, 2021). "While this discussion has focused on heart failure since motivated by ongoing Phase II trials, we propose that FPR2 agonists can reap the benefits of the biology of resolution of inflammation to re‐programme relevant target cells in a variety of diseased tissues." (PMID 32954491, 2020). "The most reasonable application of FPR2 agonists is addressed to heart failure rather than classic inflammatory pathologies." (PMID 33804219, 2021).
hepatocellular carcinoma (7 papers, 2008 to 2025). A malignant tumor that arises from hepatocytes. "One such family member, FPR2, is particularly active in certain liver diseases, including non-alcoholic fatty liver disease and hepatocellular carcinoma." (PMID 36750693, 2023). "This contest allowed us to hypothesize that ANXA1 could affect the macrophages by activating its receptor FPR, as described in the hepatocellular carcinoma where this protein is able to enhance the differentiation into M2 macrophages via FPR2 and supports their expression of IL-10." (PMID 34681678, 2021). "In hepatocellular carcinoma (HCC), it has been shown that the AnxA1 N-terminal peptide is responsible for the polarization of macrophages towards the M2 phenotype, by signaling through FPR2 and by eliciting the activation of ERK, Akt, and NFkB." (PMID 34208346, 2021).
chronic obstructive pulmonary disease (6 papers, 2013 to 2023). A chronic and progressive lung disorder characterized by the loss of elasticity of the bronchial tree and the air sacs, destruction of the air sacs wall, thickening of the bronchial wall, and mucous accumulation in the bronchial tree. "Host LL-37 has also been shown to activate FPR2 (aka FPRL1) and is considered as a proinflammatory stimulus in chronic obstructive pulmonary disease (COPD)." (PMID 37251385, 2023). "Accordingly, decreased production of LX, E-, and D-series resolvins in the airways, as well as disruption of FPR2/ALX signaling have been linked to the pathogenesis of chronic obstructive pulmonary disease (COPD), and their restoration determined beneficial effects." (PMID 29434586, 2018). "A recent study reported that serum amyloid A acting through the formyl-peptide receptor 2/lipoxin receptor (FPR2/ALX) can overwhelm anti-inflammatory signaling by LXA4 to mediate exacerbation of glucocorticoid refractory lung inflammation in patients with chronic obstructive pulmonary disease." (PMID 23508943, 2013).
Hepatic fibrosis (6 papers, 2021 to 2024). The presence of excessive fibrous connective tissue in the liver. "The administration of PD-MSCs with WKYMVm peptide improves vascular regeneration by activated FPR2 signaling while attenuating hepatic fibrosis in a rat model of liver cirrhosis." (PMID 35053347, 2022). "In conclusion, the WKYMVm alleviates hepatic fibrosis and promotes hepatic regeneration via vascular remodeling by FPR2." (PMID 33672682, 2021). "Accumulating evidence has shown that FPR2 is involved in the host’s defense against bacterial infection and inflammation in liver diseases, such as nonalcoholic fatty liver disease, liver fibrosis, and liver cancer, suggesting the pathophysiological relevance of FPR2 to the liver." (PMID 36750693, 2023). "However, Formyl Peptide Receptor 2 (FPR2) has a protective effect on the liver, and a recent animal experiment found that FPR2 expression in female mice is higher than in male mice, making females more resistant to developing hepatic steatosis and liver fibrosis." (PMID 38875754, 2024). "Because Fpr2 deficiency worsened CDAHFD-induced liver injury in female mice as much as in male mice, we examined whether the lack of Fpr2 promoted hepatic fibrosis and inflammation in female mice." (PMID 35102146, 2022).
influenza (6 papers, 2017 to 2024). An acute viral infection of the respiratory tract, occurring in isolated cases, in epidemics, or in pandemics; it is caused by serologically different strains of viruses (influenzaviruses) designated A, B, and C, has a 3-day incubation period, and usually lasts for 3 to 10 days. "Preclinical studies have shown that FPR2 antagonists protected mice from lethal infection caused by influenza and researchers have suggested that these antagonists should be explored as new influenza treatments." (PMID 35146757, 2022). "It was demonstrated that not only did the use of FPR2 antagonists protect from IAV replication in the lungs but also inhibited harmful pulmonary inflammation during severe influenza." (PMID 29738458, 2018). "In this review we will give an overview on the pathogenesis of influenza with a focus on the role of FPR2 and we will discuss the advantages of using FPR2 antagonists to treat the flu." (PMID 28928730, 2017). "In contrast, the mechanism by which FPR2 promotes severe inflammation during influenza remains to be determined." (PMID 28928730, 2017). "It is also possible that during influenza, Annexin A1 activation of FPR2 leads to pro-inflammatory signaling." (PMID 28928730, 2017). "More importantly, upon mouse infection, FPR2 activation is associated with an increase in IAV replication, an exacerbated and harmful pulmonary inflammation and a severe influenza disease." (PMID 28928730, 2017). "Altogether by inhibiting viral replication and protecting the lungs from destruction, FPR2 antagonists appear as an appealing strategy to treat or prevent influenza in the future." (PMID 28928730, 2017). "Thus, this study suggests that the use of anti-FPR2 antibodies against influenza hold great promise for the future." (PMID 29738458, 2018). "The Formyl Peptide Receptor 2 (FPR2) is a novel promising target for the treatment of influenza." (PMID 29738458, 2018). "In addition, it cannot be excluded that Annexin A1 adopts a specific structural conformation at the surface of influenza virions or heterodimerize in an unusual fashion, thereby promoting FPR2 pro-inflammatory functions." (PMID 28928730, 2017). "Since all FPR have a high degree of sequence homology, these results are consistent with the protective effect of FPR2 antagonists against flu and suggest that other FPR might be involved in IAV pathogenesis." (PMID 28928730, 2017). "Similarly, SAA binds and activates FPR2 which is used by influenza to increase viral replication." (PMID 34202272, 2021). "Thus, FPR2 represents a very attractive host target against influenza." (PMID 28928730, 2017). "Regarding FPR2, it is also a pivotal receptor involved in IAV replication and harmful inflammation of the lungs during severe influenza." (PMID 28928730, 2017). "This is of notable interest, as while it has been put forward as a potential target for influenza infection due to its role in virion internalization and persistence, this is the first report of a protozoan parasite exploiting the ANXA1/FPR2 axis to establish greater infection." (PMID 39076982, 2024). "Interestingly, a FPR2 blockade also inhibitd ERK activation and was also very efficient in protecting against influenza in preclinical models of IAV infections." (PMID 29738458, 2018). "Thus, the proof of concept that cell treatment with a monoclonal antibody directed against FPR2 efficiently inhibits virus replication opens the door to novel anti-FPR2 immunotherapy against influenza." (PMID 29738458, 2018).
ischemic stroke (6 papers, 2017 to 2023). A stroke disorder caused by obstruction of blood flow to the brain, due to thrombotic (local blood clot formation) or embolic (due to a blood clot or other material traveling from another site) event. "Both FPR2 and ChemR23 are implicated in inflammatory brain disorders including ischemic stroke and Alzheimer’s, and findings herein extend those actions to PAE." (PMID 37483341, 2023). "In recent years, studies have reported that LXA4 exerts a notable anti-inflammatory and neuroprotective effect by activating its receptor formyl peptide receptor 2 (FPR2) in animal models of ischemic stroke, subarachnoid hemorrhage and ICH." (PMID 36100985, 2022). "LXA4 binds the lipoxin receptor (ALX)/formyl peptide receptor 2 (FPR2) and mediates the resolution of inflammation in bowel and lung disease and ischemic stroke; however, there is little knowledge of its role in hemorrhagic stroke." (PMID 35203926, 2022). "ANXA1 via its receptor FPR2 has been shown to mitigate cerebrovascular injury by limiting immune cell infiltration and pro-inflammatory thrombotic cytokine production in mouse models of ischemic stroke." (PMID 37208759, 2023).
astrocytoma (5 papers, 2008 to 2023). "The activation of FPR2 by WKYMVM in human U87 astrocytoma and FPR2-transfected CHO cells triggers JNK, ERKs and p38MAPK phosphorylation." (PMID 23549262, 2013). "The activation of FPR2 by WKYMVm in human astrocytoma cells also results in Ca2+ influx and in the phosphorylation of inhibitory-κB kinase (IKK), which is prevented by pre-treatment of PTX and requires ERKs, PI3K and c-Src activation." (PMID 23549262, 2013).
bacterial meningitis (5 papers, 2011 to 2022). Inflammation of the membranes surrounding the brain and spinal cord due to a bacterial infection. "In summary, this study demonstrates anti-inflammatory properties of Ac2-26 in a model of bacterial meningitis, which are mediated via FPR2, but not FPR1." (PMID 33121515, 2020). "Future studies have to address whether the neutrophil phagocytosis by microglial cells takes place during bacterial meningitis, and whether such a presumably protective effect is mediated by FPR in general, and by FPR2 in particular." (PMID 33121515, 2020). "We and others have previously shown that the expression of both, Fpr1 and Fpr2, is altered in various inflammatory and neurodegenerative animal models including APP/PS1 double-transgenic, in a model of acute, metabolic oligodendrocyte injury, or in a model of bacterial meningitis." (PMID 32331524, 2020).
Cerebral ischemia (5 papers, 2018 to 2024). Restriction of arterial blood supply to the brain associated with insufficient oxygenation to support the metabolic requirements of the tissue. "The role of ALXR/FPR2 activation was also shown in a cerebral ischemia–reperfusion injury model, where LXA4 induced microglial polarization towards an M2 phenotype that can more effectively remove DAMPs by efferocytosis." (PMID 38396985, 2024). "The activation of Fpr2/3 in neutrophils by aspirin-triggered lipoxin A4 has affected the formation of neutrophil and platelet aggregates during cerebral ischemia/reperfusion injury." (PMID 36834844, 2023). "Additionally, FPR 2/LXA4 Receptor can regulate neutrophil-platelet aggregation and attenuate cerebral inflammation after cerebral ischemia/reperfusion injury in a recent murine model." (PMID 29544524, 2018). "Research shows that mice without homolog of ALX/FPR2 show exacerbated inflammatory response after cerebral ischemia and reperfusion." (PMID 33921615, 2021).
diabetes (5 papers, 2017 to 2024). "Interestingly, treatment with LXA4 significantly attenuated the diabetes-induced increase in mFpr1 and mFpr2 expression, as well as downregulating mSaa1, consistent with the observations of Aubeux and colleagues who reported that the gene expression of FPR2 was downregulated in M2-like macrophages." (PMID 39563316, 2024). "Similar to REC and diabetic retina; however, Compound 49b significantly reduced 5-LOX enzyme levels in Müller cells cultured in high glucose, as well as increased ALX/FPR2 levels, suggesting a potential regulatory pathway in Müller cells, albeit much less responsive." (PMID 29095817, 2017).
Insulin resistance (5 papers, 2020 to 2025). Increased resistance towards insulin, that is, diminished effectiveness of insulin in reducing blood glucose levels. "Recently, a study indicated that FPR2 deficiency can alleviate diet-induced insulin resistance, which is by weight loss and inhibiting inflammation." (PMID 33995497, 2021). "It is possible that ALX/FPR2 deficiency could drive weight gain and insulin resistance." (PMID 40972651, 2025). "In addition, myeloid-specific deletion of Fpr2 alleviated diet-induced liver damage, insulin resistance, and macrophage infiltration." (PMID 36750693, 2023).
viral infection (5 papers, 2018 to 2025). "While this is potentially true for some viral infections, including arbovirus diseases, other viruses have evolutionarily developed strategies to hijack the AnxA1/FPR2 axis, to infect and replicate more effectively." (PMID 37190040, 2023). "Because the contribution of this signaling axis in viral infections is undefined, we investigated AnxA1-mediated FPR2 activation on influenza A virus (IAV) infection in the murine model." (PMID 31398292, 2019). "During viral infection, FPR2 is activated by annexinA1, which is present in the envelope of influenza viruses; this activation promotes virus replication." (PMID 29738458, 2018). "In HIV-1 infection, FPR2 on the one hand may inhibit viral infection through HIV-1 co-receptor CCR5 and CXCR4 cross-desensitization mediated by activation through glycoprotein fragments, but on the other hand can act as a co-receptor for HIV-1 viral entry itself." (PMID 40703440, 2025).
amyloid (4 papers, 2012 to 2025). "SAA receptors, such as SELS (glucose homeostasis and ER stress), ABCA1, ABCA7, SCARB1 (cholesterol efflux), CD36, TLR2, TLR4, CST3 (inflammatory signaling), FPR2 (chemotaxis and immune cell activation), and AGER (amyloidosis), have been reported previously." (PMID 27799725, 2016).
Anxiety (4 papers, 2014 to 2023). Intense feelings of nervousness, tension, or panic often arise in response to interpersonal stresses. "We report here that both FPR2 and ChemR23 are essential for healthy brain development, and their loss-of-function leads to greater measures of anxiety and perhaps deficits in memory." (PMID 37483341, 2023). "While it has been studied for some time, it has just recently been classified as an FPR2 agonist and has further demonstrated an ability to produce anxiolytic-like effects, thus alleviating some symptoms associated with anxiety." (PMID 31336833, 2019). "The results of this study suggest that genetic deletion of Fpr2/3 in mice causes significant changes in anxiety-related behaviour." (PMID 25517119, 2014). "MMK-1, an FPR2 agonist, is by far the more commonly used peptide, and studies have shown that it may be useful as an anti-anxiety drug, as well as a drug to counteract hair loss from chemotherapy." (PMID 31336833, 2019). "To investigate whether reduced anxiety of Fpr2/3-/- mice was linked to an increased preference for novelty, indicative of low anxiety, we next assessed the performance of animals on a novel object recognition task." (PMID 25517119, 2014). "Here we demonstrate that Fpr2/3-deficient mice show a distinct profile of behaviour characterised by reduced anxiety in the marble burying and light-dark box paradigms, increased exploratory behaviour in an open-field, together with superior performance on a novel object recognition test." (PMID 25517119, 2014). "The latency to start this behaviour was also significantly increased in Fpr2/3-/- mice consistent with reduced anxiety." (PMID 25517119, 2014). "In the present study we investigated various anxiety-related behaviours in Fpr2/3-/- mice, including responses to novelty and aversive contextual stimuli, and compared the selectivity of these responses with low anxiety-provoking behaviours." (PMID 25517119, 2014). "In one study FPR2 KO animals show increased activity, increased time in the light side of the light–dark box, and increased recognition memory (using the novel object recognition test) than WT, interpreted as evidence of lower anxiety." (PMID 37483341, 2023). "Fpr2 also proved to mediate anxiety as shown by effects reported for Fpr agonists." (PMID 32922257, 2020). "We next investigated whether the reduced anxiety of Fpr2/3-/- mice could be mimicked by administering the FPR inhibitor Boc2 in wild type animals." (PMID 25517119, 2014). "The present study confirms and extends these findings by revealing reduced anxiety of Fpr2/3-/- mice on a range of tests of anxiety, including open-field and climbing exploratory behaviour, choice preference for aversive versus non-aversive contexts, and novel versus familiar objects." (PMID 25517119, 2014). "Pharmacological blockade with a formyl peptide receptor antagonist, Boc2, in wild type mice reproduced most of the behavioural changes observed in the Fpr2/3-/- mice, including a significant improvement in novel object discrimination and reduced anxiety in a light/dark shuttle test." (PMID 25517119, 2014). "In the absence of PAE, ChemR23 KO animals showed decreased anxiety-like behavior on the elevated plus maze and FPR2 KO had poor grip strength and low activity compared to age-matched WT mice." (PMID 37483341, 2023).
chorioamnionitis (4 papers, 2020 to 2022). A morphologic finding indicating inflammation of the fetal sac membranes. "Besides, RvD1 alleviates inflammation in trophoblasts caused by chorioamnionitis in vivo and in vitro through the FPR2/NF‐κB pathway." (PMID 36301030, 2022). "Our previous study indicated that RvD1 alleviated the inflammation of trophoblasts in vivo and in vitro by combining with FPR2 in chorioamnionitis." (PMID 35018584, 2022).
depression (4 papers, 2020 to 2023). "Thus, despite some beneficial influence on neurogenesis, FPR2 might exacerbate the impairment of NSCs under conditions associated with chronic inflammation, such as Alzheimer's Disease and depression." (PMID 34345870, 2021). "It has been showed that CSF3R is a cytokine that controls neutrophil expansion and differentiation, and can serve as a biomarker for neuromodulation; FPR2 knockdown may maintain hippocampal homeostasis by preventing depression-related neuronal damage." (PMID 37649561, 2023). "Also, in studies using the murine model of depression, RvD1 has been shown to have an antidepressant effect, strongly dependent on the activation of FPR2 and in consequence, on MAP/ERK, PI3K/Akt but also AMPA signaling." (PMID 34105114, 2021). "Moreover, FPR2/3 knockout in a mouse model of depression ameliorated anxiety and depression-like behaviour, while limiting neuronal death in the hippocampus." (PMID 34345870, 2021). "In fact, the absence of ANXA1 protein even more than the absence of its main receptor (namely FPR2/3) is indispensable to the suppressive action of glucocorticoids on the HPA axis, as well as to the hippocampal homeostasis by preventing neuronal damage in the course of depression." (PMID 34105114, 2021).